MMP9 (matrix metallopeptidase 9)
Diseases named in the same sentence as MMP9 in open-access papers (continued):
Sharing a sentence is not in itself a finding about the gene and the disease.
asthma (continued). "They further demonstrated that TGF-β1 released from eosinophils further induced MMP-2, MMP7, MMP9 and MMP12 which are all essential for abnormal matrix turnover and myofibroblast differentiation in asthma fibrosis." (PMID 36911735, 2023). "Immunohistochemistry also showed that there was a marked increase in iNOS, MMP-2, MMP-9, and COX-2 in vehicle-treated asthma lungs." (PMID 36755351, 2023). "The imbalance between MMP-9 and TIMP-1 is recognized as an important theory to explain the development of airway remodeling in asthma." (PMID 36945930, 2023). "Asthma-derived eosinophils also stimulated an increased expression of MMP2, MMP-9, MMP-12, TGF-β1 and TGF-β2 in MRC-5 fibroblasts also in correlation with an abnormal matrix turnover and airway fibrosis." (PMID 36911735, 2023). "IPA analyses of increased abundance of the four proteins (MMP9, AGT, S100A8, CTSC) in the POLD group (when compared to PTc) suggested increased neutrophil accumulation, which is a reasonable hypothesis given the association of neutrophilic inflammation with wheezing in asthma." (PMID 37474963, 2023). "The increase in MMP-1, MMP-2, MMP-8, and MMP-9 expression levels were found in sputum and bronchoalveolar lavage (BAL) from patients with asthma or COPD." (PMID 36142454, 2022). "This is the case for MMP-9, the levels of which are increased in BAL fluid from patients with asthma, and its role in controlling the T-cell response to allergens and in airway remodeling has been proven." (PMID 36611613, 2022). "Plasma concentrations of the neutrophil-derived mediators MPO, matrix metallopeptidase 9 (MMP-9) and CXCL8 were augmented in patients with asthma compared to healthy subjects, which suggests that PMNs are activated in vivo." (PMID 36359917, 2022). "Elevated levels of MMP-9 and MMP-13 were found in the serum, sputum and BALF of patients with classic asthma." (PMID 35721212, 2022). "Similar results were found in other asthma studies—the MMP-2 and MMP-9 levels were higher in asthmatic airways than in healthy ones." (PMID 35456903, 2022). "LAS194046 shows similar maximal % inhibition and potency inhibiting IL-8, MMP-9 and superoxide anion release in neutrophils from healthy, COPD and asthma." (PMID 35332239, 2022). "NET components, such as high-mobility group box 1 protein (HMBG1), can activate BECs to release several mediators involved in asthma pathogenesis, including TSLP, TNF-α, MMP-9, and VEGF." (PMID 36359917, 2022). "Unlike fluticasone propionate, the pan-JAK inhibitor LAS194046 showed similar efficacy inhibiting IL-8 and MMP9 release in neutrophils form healthy subjects and COPD patients and in a lesser extent in severe asthma." (PMID 35332239, 2022). "Matrix metalloproteinase-9 (MMP-9) plays a key role in the development of airway inflammation and facilitates angiogenesis in asthma." (PMID 34342773, 2022). "Plasma levels of several biomarkers of neutrophils activation such as MPO, MMP-9 and CXCL8 were increased in asthma patients compared to healthy subjects." (PMID 34342773, 2022). "Using an ovalbumin (OVA)-induced asthma rat model, it has been found that NGF aggravates inflammation, AHR, and airway remodeling via the Th2 immune response and by increasing matrix metalloproteinase-9 (MMP-9) expression." (PMID 34502019, 2021). "The inhaled corticosteroid (ICS), beclomethasone dipropionate (BDP), attenuated the expression of submucosal MMP-9 and increased that of submucosal TIMP-1, suggesting corticosteroid treatment of asthma to ameliorate angiogenesis." (PMID 33628848, 2021). "It is known that TIMP-1 binds and inactivates matrix metalloproteinases (MMP), specifically MMP-2 and MMP-9, with imbalances of the MMP-9/TIMP-1 interactions posited in the development of asthma." (PMID 34221020, 2021).
asthma (continued). "The MSC-pANGPT1 (angiopoietin 1 gene) were aerosolized in a rabbit OVA-induced asthma and reduced the expression of pro-inflammatory cytokine genes (IL-4, TNF, TGF-β, and MMP-9), which can be an additional beneficial effect in asthma treatment." (PMID 33959015, 2021). "The amount of MMP9 in BALF directly correlates with the disease severity and decline in lung function in asthma." (PMID 35387021, 2021). "Increased level of MMP-9 was found in exhaled breath condensates, bronchoalveolar lavage fluid (BALF), and sputum of patients with asthma and COPD." (PMID 32829707, 2020). "In bronchial epithelial cells, AhR agonists led to the upregulation of MMP2, MMP9, and MMP1 and proposed to contribute to airway remodeling in asthma and chronic obstructive pulmonary disease." (PMID 33488929, 2020). "MMP-9 has a pivotal role in remodeling and was the first to be investigated in asthma Elevated MMP levels, particularly MMP-9, are detected in the BAL fluids and even in the sera of asthmatic patients." (PMID 32054098, 2020). "The airways of asthma with greater yearly decline in FEV1 showed an increased thickness of submucosa and strong expression of MMP-9." (PMID 31547356, 2019). "The increase of oxidative stress and subsequent enhancement of MMP9 and TGF-β1 expression were rescued by the administration of Tetrandrine in the rat model of asthma." (PMID 31781316, 2019). "Hoshino and colleagues found that corticosteroid treatment can decrease the deposition of subepithelial collagen through downregulation of MMP-9 and upregulation of TIMP-1 in asthma." (PMID 31547356, 2019). "A disintegrin and metalloproteinase-33 (ADAM-33), TGF-β, vascular endothelial growth factor, matrix metalloproteinase-9 (MMP-9), IL-5, IL-13, and IL-14 are key mediators involved in airway remodeling in asthma." (PMID 31284537, 2019). "The same authors have stressed the potential importance of MMP-9 and TIMP-1 imbalance in asthma by showing that the basal airway caliber was related to the ratio of MMP-9 to TIMP-1." (PMID 31547356, 2019). "Other authors also showed increased activities of elastinolytic MMP-9 and MMP-13 as well as collagenolytic MMP-8 in equine asthma." (PMID 31316303, 2019). "Indeed, anti-TNF-α therapy has been reported to reduce the expression of MMP-9 as well as that of other inflammatory cytokines (e.g., IL-4, IL-13, and IgE), thereby hindering the recruitment of inflammatory cells and inhibiting the airway inflammation in asthma." (PMID 26783416, 2016). "To elucidate the immunologic mechanism of TCM in the treatment of asthma, we examined the expression of some more cytokines related to asthma, including IL-10, IL-17, TGF-β1, and MMP-9 in this study." (PMID 27378824, 2016). "Patients with asthma showed an increased gelatinolytic activity derived from MMP-2 and MMP-9 in their sputum." (PMID 27455234, 2016). "Despite numerous studies conducted so far, current knowledge regarding the role of MMP-9 in COPD and asthma is still incomplete." (PMID 26123447, 2016). "MMP-9 is believed to play an important role in airway remodeling in chronic airway diseases and MMP-9 expression is closely related to the severity of asthma." (PMID 28050193, 2016). "Another observation concerned the shifted ratio of MMP-9 to its natural inhibitor—TIMP-1—in bronchoalveolar lavage (BAL) fluid, which was higher in children with symptomatic asthma, as compared to that of healthy controls." (PMID 26123447, 2016). "To conclude, we demonstrate that OSA is associated with specific changes in airway inflammation associated with predominant neutrophilic inflammation with high levels of MMP-9 and IL-8 and low RBM thickness in patients with severe asthma." (PMID 26934051, 2016). "The expression levels of the classical inflammatory biomarkers such as IgG, IgE, MMP9, IFN-γ, IL-4, and ICAM-1 that play an important role in the pathogenesis of asthma were also assessed." (PMID 28050193, 2016).
asthma (continued). "Others have demonstrated that MMP9, which is abundantly present in neutrophils, prevents AHR in asthma models." (PMID 26284919, 2015). "Therefore, high MMP-9/EBC activity associated with an increased total IgE level could presumably be considered as a risk marker of airway remodeling and poor clinical prognosis in asthma course, but this issue still requires further studies." (PMID 25650123, 2015). "High levels of MMP-9 were found in mucosal biopsies, sputum and in exhaled breath condensates (EBC) of asthma patients." (PMID 25650123, 2015). "To clarify the mechanism of LXRs in remodeling process of asthma, we investigated the TGF-β1 in BALF and MMP-9 expression in lungs of animals." (PMID 24681543, 2014). "Ratios of MMP-9/TIMP-3 were decreased in both uncontrolled and controlled asthma compared to healthy controls." (PMID 24950767, 2014). "In this study we found that plasma levels of 8-isoprostane, CRP, total MMP-9, and 92-KDa MMP-9 activity were significantly increased in patients with asthma in acute exacerbation and decreased in remission but remained elevated compared with healthy controls." (PMID 24073339, 2013). "The PPI network, which had 31 nodes and 68 edges, was constructed using the intersection of AFB1 and asthma target genes In this study, PTGS2, ADRB2, MMP9, CysLTR1, and PTGS1 were the top five targets according to degree value, representing the hub targets of AFB1-induced asthma." (PMID 41557720, 2026). "Finally, we obtained 7 predicted targets of baicalein for asthma treatment, namely AKT1, VEGFA, EGFR, SRC, MAPK3, MMP9, MAPK1." (PMID 38178132, 2024). "Furthermore, western blot analysis further confirmed that BIBF1000 treatment attenuated the lung expression of α-SMA, PCNA, iNOS, MMP-2, MMP-9, and COX-2, compared to vehicle-treated asthma lung tissues." (PMID 36755351, 2023). "Intranasal CUR reduced protein expressions of MMP9, histone deacetylase 1, histone H3 acetylation at lysine 9, and NF-κB p65, suggesting that intranasal administration of CUR can be effective in preventing asthma severity." (PMID 37513300, 2023). "In lung tissues from the asthma model mice, mucus production and gene expression of mucin 5B, p38, and MMP9 were elevated, compared to the non-asthmatic mice." (PMID 37513300, 2023). "These uPA‐uPAR pathway components showed modest correlated expression with suPAR protein levels (uPA r = 0.40 (p = 0.02), PAI‐1 r = 0.41 (p = 0.016) MMP‐9 r = 0.37 (p = 0.04)) in cells from asthma patients not from control subject cells." (PMID 37876037, 2023). "MMP-9 levels were increased in the BAL and sputum of patients with asthma after allergen challenge." (PMID 36359917, 2022). "MMP-9, also known as gelatinase B, is a potent extracellular matrix (ECM) degrading enzyme, considered as one of the main effector proteases of tissue remodeling in other chronic inflammatory lung diseases such as COPD and asthma." (PMID 36362203, 2022). "Furthermore, in conditions such as asthma and chronic obstructive pulmonary disease, WT1 was reported to act as a repressor of MMP-9." (PMID 35243014, 2022). "The elevated levels of JAK2 and JAK3 in neutrophils from COPD and severe asthma patients could explain the efficacy of LAS194046 inhibiting IL-8 and MMP9 release, as well as the inhibition of ROS production that we observed." (PMID 35332239, 2022). "Upregulated MMP-9 induces leukocyte recruitment in lung diseases including COPD and asthma." (PMID 36142454, 2022). "Thus, we further validate its anti-fibrotic role in asthma by identifying two critical remodeling mediators, TGF-β promoting extracellular matrix (ECM) deposition and MMP-9 degrading ECM." (PMID 35153777, 2022). "UPM exposure did not change MMP9 mRNA expression in control, asthma or COPD group in any of the epithelial co-cultures." (PMID 34168212, 2021). "Eosinophils produce increased levels of MMP-9, ROS as well as TGF-β in asthma." (PMID 32155894, 2020).
asthma (continued). "Our results revealed the expression of MMP-1, MMP-9 in the nasal tissues, and maximal AE bone thickness on CT scans were greater in smokers with asthma and CRS than in asthmatic non-smokers with CRS and asthmatic non-smokers without CRS." (PMID 31653934, 2019). "MMP-9 was the first MMP to be investigated in depth for its role in the development of asthmatic pathology and was also the most highly expressed MMP in the BAL fluid and sputum of asthma patients." (PMID 31547356, 2019). "In severe equine asthma, increased MMP-2 and MMP-9 levels were shown using gelatin zymography." (PMID 31316303, 2019). "The level of the active form of MMP-9 was not significantly different between asthma patients and controls." (PMID 31428095, 2019). "Additionally, there were increases in the number of cells positive for ROCK1, ROCK2, TGF-β, MMP-9, MMP-12, and TIMP-1, and the percentages of isoprostane, biglycan, decorin, fibronectin, and collagen fibers, in the asthma group." (PMID 30979017, 2019). "Several studies have shown that MMP-9, an enzyme that promotes cleavage of the ECM by degrading structural proteins such as collagen, plays a crucial role in the pathogenesis of airway inflammation and remodeling in asthma." (PMID 26783416, 2016). "Similarly to asthma-suffering individuals, also COPD patients displayed increased MMP-9 serum levels, which moreover correlated negatively with the Tiffeneau–Pinelli index (FEV1/FVC ratio)." (PMID 26123447, 2016). "In the current study, we found that morin significantly attenuated MMP-9 expression, which might have contributed to the lessened ECM, thereby contributing to its positive effects on asthma." (PMID 26783416, 2016). "Besides the reported correlation between some MMP-9 SNPs and cancer metastasis, aneurysm formation and atherosclerosis in coronary arteries and also their possible involvement in COPD and asthma have been postulated." (PMID 26123447, 2016). "Other inflammatory mediators, which play a role in asthma, include matrix metalloproteinases (MMP), including MMP-9 and ADAM-33 (a disintegrin and metalloproteinase-33); chemokines including eotaxins, RANTES, and MCP-1; chemokine receptors, CCR-3 for eotaxin, CCR-5 for RANTES, and CCR-2 for MCP-1." (PMID 25642424, 2015). "Therefore, the aim of the study was to assess the amount and activity of MMP-9 in context of pro-inflammatory cytokines (IL-6, IL-8 and tumor necrosis factor, TNF), measured in EBC of asthma-suffering children, treated with inhaled steroids." (PMID 25650123, 2015). "Interestingly, the activity of MMP-9/EBC in our patients was higher than in health controls, despite relatively mild symptoms of asthma, possibly due to prolonged treatment with inhaled corticosteroids." (PMID 25650123, 2015). "In this study, we investigated the anti-inflammatory effects of Crataegus pinnatifida ethanolic extracts (CPEE) on Th2-type cytokines, eosinophil infiltration, expression of matrix metalloproteinase (MMP)-9, and other factors, using an ovalbumin (OVA)-induced murine asthma model." (PMID 23029210, 2012). "Genotyping of four HapMap derived tagging SNPs in the MMP-9 gene was performed using MALDI-TOF MS in three cross sectional study populations of German children (age 9-11; N = 4,264) phenotyped for asthma and atopic diseases according to ISAAC standard procedures." (PMID 20181264, 2010). "MMP-9, present in tertiary granules of neutrophils, was found in BAL of asthmatics and it was correlated to the absolute neutrophil count, MMP-9−/− mice showed reduced immune cell infiltration and bronchial hyperresponsiveness compared to wild type mice in a murine model of asthma." (PMID 34342773, 2022). "A caveat to consider is that although TIMP1 and MMP9 enzyme activities have been associated with decline in lung function, the ratio of MMP9/TIMP1 does not necessarily correlate with the disease severity in asthma." (PMID 35387021, 2021).
asthma (continued). "Most importantly, alveolar macrophages (AMs) from chronic asthma with a fast FEV1 decline spontaneously released a higher amount of MMP-9 (8.52 ± 3.53 ng/mL, n = 8, p < 0.05) than those of asthma with a slow FEV1 decline (0.99 ± 0.20 ng/mL, n = 13) or normal subjects (0.47 ± 0.20 ng/mL, n = 10)." (PMID 31547356, 2019). "The ratio of MMP-9/TIMP-1 in the sputum of asthmatic patients has been shown to decrease after recovery from an acute exacerbation of asthma, which may imply that MMP9/TIMP has a negative correlation." (PMID 31547356, 2019). "In contrast, no such MMP-9 increase was found in patients with allergy, but without asthma." (PMID 26123447, 2016). "Both MMP-2 and MMP-9 could promote the egress of inflammatory cells into airway lumen, an essential mechanism by which each MMP could exhibit a protective anti-inflammatory role in asthma." (PMID 27455234, 2016). "Thus, it is not surprising that a previous study was unable to identify an effect of MMP-9 variations in unstratified asthma, as in that case-control study atopic and non-atopic asthma were not analyzed separately." (PMID 20181264, 2010). "Based on the relevance of MMP-9 in both inflammation and airway remodeling, it was hypothesized that genetic variations in the MMP-9 gene could be involved in different forms of wheezing and asthma." (PMID 20181264, 2010). "Neutrophil-derived, MMP-9-mediated tissue degradation and the instructional role of MMP-9 in directing the inflammatory response are key, and perhaps critical, events in the etiology of chronic obstructive pulmonary disease (COPD); systemic and cerebral vascular diseases, asthma, and periodontitis." (PMID 18412948, 2008). "However, this cannot explain why MMP-9 is acting differently in atopic and non-atopic inflammation and why the negative effect of increased remodeling due to changes in a matrix metalloproteinase becomes more important in the non-atopic asthma." (PMID 20181264, 2010). "Inhaled steroids did not reduce the exhaled MMP-9 rate, and this trend was also observed in BAL fluids of steroid responder and non-responder patients with asthma." (PMID 32054098, 2020). "Protein analyzed by western blotting confirmed the results of mRNA and revealed that smokers with CRS and asthma had higher levels of MMP-1 (P = 0.032) and MMP-9 (P = 0.042) expression than those of non-smokers with CRS and asthma." (PMID 31653934, 2019). "The mRNA expression of MMP-1 (P = 0.043) and MMP-9 (P = 0.003) was significantly up-regulated in the nasal tissues of smokers with CRS and asthma compared to those of non-smokers with asthma and CRS." (PMID 31653934, 2019). "A key observation in our study was that MMP-7, MMP-9, and MMP-10 concentrations remained similar across all the investigated groups, indicating that they may not possess any prognostic value in asthma." (PMID 38275403, 2024). "The median concentration in LC patients compared to healthy non-smokers, asthma sufferers, and smokers was more than 200% higher in SAA (771%), MMP-9 (743%), IL-8 (535%), CXCL9/MIG (482%), TNFRI (406%), Gro (331%), MPO (300%), Rantes (274%), Resistin (271%), TNFRII, and MIF (219%)." (PMID 32085733, 2020). "Hypoxia, which is associated with extracellular matrix remodeling in inflammatory lung diseases, such as fibrosis, COPD, and asthma, upregulated the expression of MMP-1, MMP-2, and MMP-9 precursors without subsequent activation in human lung fibroblasts and pulmonary vascular smooth muscle cells." (PMID 23226927, 2012). "While this MMP9 rs2274755 has been investigated in several studies, none of these studies have examined its impact on the efficacy of BVZ treatment in mCRC patients, and available data suggest that this SNP might be involved in the development of asthma." (PMID 33573134, 2021).